TIMP2 (TIMP metallopeptidase inhibitor 2)
Diseases named in the same sentence as TIMP2 in open-access papers (continued):
Sharing a sentence is not in itself a finding about the gene and the disease.
cancer (continued). "The endogenous tissue inhibitor of metalloproteinase-2 (TIMP-2), through its homeostatic action on certain metalloproteinases, plays a vital role in remodelling extracellular matrix (ECM) to facilitate cancer progression." (PMID 36585738, 2022). "In summary, expression profiling of 2 human cancer cell lines identified several components of the PI3K/AKT pathway and the MMP inhibitor TIMP2 as candidate MCM7 targets." (PMID 35192608, 2022). "As introduced previously, TIMP2 was related to TMB, MSI, and neoantigen in varying degrees, providing a theoretical basis for directing patient-specific cancer immunotherapy optimizing clinical benefit of current immunotherapy." (PMID 36304987, 2022). "Interestingly, while TIMP-1 plasma levels were high, TIMP-2 amounts were low in all cancer subjects and these differences could be due to the characteristic activation mechanism of proMMP-2 and proMMP-9 that includes the participation of TIMP-2 and TIMP-1, respectively." (PMID 36213817, 2022). "Given that neovascularization occurs in both cancers and ROP, studies have discussed the correlation between TIMP-2 and ROP or retinal neovascularization." (PMID 36430677, 2022). "TIMP2 was a kind of matrix metalloproteinases (MMP) inhibitor, while MMPs were intriguing genes frequently up-regulated in most cancers." (PMID 35300408, 2022). "TIMP-1 and TIMP-2 play a crucial role in extracellular matrix (ECM) regulation, wound healing, pregnancy and cancer, and there is increasing evidence that they are immune-modulatory." (PMID 34638439, 2021). "The majority of MMPs and TIMPs were mainly expressed in cancer cells at the invasive front (MMP-9: 97.3% of the tumors, MMP-11: 98.7%, MMP-14: 94.0%, TIMP-1: 86.7%, TIMP-2: 96.7%)." (PMID 33669393, 2021). "Tissue inhibitor of metalloproteinases 2 (TIMP2), a secreted 21 kDa multifunctional protein and a member of TIMP gene family, could inhibit matrix metalloproteinases (MMPs), which was associated with degradation of extracellular matrix and was a key role in cancer metastasis." (PMID 34678879, 2021). "We also observed significantly higher concentrations of TIMP-2 in stages III and IV of cancer compared with stage I or II (TIMP-2: I vs. III and IV p < 0.05 and II vs. III and IV p < 0.05)." (PMID 30820752, 2020). "Extensive genes have been identified as the target of miR-761 in numerous cancers, including HDAC1, Rab3D, Runx3, Mitofusin-2, CXCR1, TRIM29, MSI1, ING4, TIMP2, and GSK3β." (PMID 32185226, 2020). "The gene set enrichment analysis revealed that these interacting proteins also interacted with cancer-related proteins, including KISS1, TIMP2, MMP11, IGFBP1, EGFR, and CDKN1C." (PMID 32117443, 2020). "On the other hand, it has been reported that theincidence of cancer is increased when the actions of TIMP-1 and TIMP-2 are abnormal,and increased expression of TIMP-1 has been suggested to be a useful basis fordiagnosing of malignant tumors." (PMID 33152052, 2020). "Similar to TIMP-2, it has been found that TIMP-4 is upregulated or downregulated in several types of cancer." (PMID 33419373, 2020). "The concentrations of MMP-2 and TIMP-2 measured separately in cancer patients are notable, and the sensitive relationship between MMP-2 and TIMP-2 is also of great interest among scientists and clinicians." (PMID 32751899, 2020). "CDKN2A (p16), used as a key biomarker for HPV status, exhibited the most extensive hyper-5hmC in HPV(+) tumors, while HPV(−) tumors showed hyper-5hmC in CDH13, TIMP2, MMP2 and other cancer-related genes." (PMID 33203436, 2020). "EV-derived TIMP-2, on the other hand, plays a crucial role in the formation of the MT1-MMP-TIMP-2-pro-MMP-2 ternary complex for MMP-2 activation, which is well known for its impact on cancer progression." (PMID 32610589, 2020). "Both RANTES and IL-8 are suggested to rather promote than reduce cancer cell invasion, so we focused on the further examination of TIMP1 and TIMP2." (PMID 31836008, 2019).
cancer (continued). "There are studies reported that miR-93 can promote different cancer cells proliferation, migration and progression by targeting PPARGC1A 24, PTEN 25, RB1 26, TIMP2 27, and so on." (PMID 31737116, 2019). "We found that lower TIMP-2 or/and higher MMP-9 expression in cancer tissues was correlated with poorer overall survival (OS)." (PMID 31293204, 2019). "This indicates that actein can upregulate the expression of inhibitors TIMP-1 and TIMP-2 but downregulate the expression of MMP-9 and MMP-2, thereby resulting in the suppression of cancer metastasis." (PMID 30618758, 2018). "Proteins involved in cancer cell invasion, including TIMP-1, TIMP-2, and CD147, were expressed at increased levels after ANDR treatment." (PMID 28194420, 2017). "IIF also induced differentiation in several cancer cell lines, inhibited MMP-2 and MMP-9 and increased expression of their inhibitors (TIMP-1 and TIMP-2)." (PMID 28465354, 2017). "TIMP2, besides its activity in regulating MMPs, including MMP2, has a role in negatively regulating cellular response to growth factors, thus arresting cancer sprouting." (PMID 27288264, 2016). "Whereas all of the assessed genes showed high expression in fibroblasts, several genes, including SPARC, ADAM12, TIMP2, MMP2, and COL5A2 were also expressed in carcinoma cells, albeit at lower levels." (PMID 27128408, 2016). "Determined by MTT assay, both of the TIMP2-based, enediyne-integrated fusion proteins LDP(AE)-TIMP2 and TIMP2-LDP(AE) displayed highly potent cytotoxicity to the tested cancer cell lines." (PMID 26314845, 2015). "In vitro study, MMP-14 is known as an important activator of pro-MMP-2 at the cell surface via the involvement of TIMP2; for this reason, the interactions among MMP-14, TIMP2 and MMP-2 are of importance in cancer cell invasion and migration." (PMID 26314845, 2015). "We demonstrated that MMP-2 serum levels were significantly higher in patients with positive expression of this enzyme in cancer cells and in CRC patients with positive expression of TIMP-2 in inflammatory and normal cells." (PMID 24395652, 2014). "Tissue inhibitor of metalloproteinase (TIMP2) is involved in the regulation of matrix metalloproteinase 2 (MMP2) and shown to implicate in cancer development and progression." (PMID 25136829, 2014). "Among TIMP members, TIMP-2 is most frequently investigated because it is a unique member of the TIMP family and involved in cancer progression and metastasis." (PMID 21152266, 2010). "Over expression of TIMP-2 can inhibit the activity of MMP-2 and it also inhibits the invasive and metastatic behaviors of cancer cells." (PMID 19636436, 2009). "Instead, we noted that MMP-13, both in cancer cells and peritumoral fibroblast cells, correlated with TIMP-1 and TIMP-2 (to a lesser extent)." (PMID 18373849, 2008). "Constitutive expression and activity of MMPs increases the invasiveness of various types of cancer cells, and we have determined characterized the expression of MMP-2, MMP-9 and MMP-14 as well as TIMP-1 and TIMP-2 mRNA in EN-1078D cells, using RT-PCR." (PMID 17894888, 2007). "We evaluated urine NGAL, KIM-1, TIMP-2, and IGFBP-7, collected during cisplatin infusions early in cancer therapy (early visit [EV]) and later in cancer therapy (late visit [LV]), for predicting signs of CKD and HTN at 3 months after cisplatin therapy completion." (PMID 38668904, 2024). "In fact, mechanistic and preclinical studies have established TIMP2 as a promising anti-cancer biomolecule, currently under notable preclinical development against a wide variety of human cancers." (PMID 36060252, 2022). "MMP14 plays a crucial role in cancer migration and metastasis by ECM remodeling and cell motility, and MMP14 responses can be regulated by the scaffolding protein NEDD9 (neural precursor cell expressed developmentally downregulated 9) and TIMP2 levels." (PMID 36624735, 2022). "More importantly, TIMP2 and TIMP3 have been identified as novel biomarkers for cancers." (PMID 36494333, 2022).
cancer (continued). "Of these, 10 were expressed in cancer-associated fibroblasts (CAFs) and were increased in ILC compared to IDC in bulk gene expression datasets, with PAPPA and TIMP2 being associated with better survival in ILC but not IDC." (PMID 35205651, 2022). "Compared with the constant and opposing patterns of TIMP-1 and TIMP-3, variable trends have been reported for TIMP-2 and TIMP-4 in human cancer, which could due to the heterogeneity of the types and stages of cancer." (PMID 33419373, 2020). "In case of TIMP-2, most cancer tissues were negative, whereas few malignant cells displayed moderate cytoplasmic immunoreactivity." (PMID 32984024, 2020). "Treatment with cancer cells-derived exosomes increased expression of these ECM mediators but not TIMP-2." (PMID 32427870, 2020). "We evaluated the concentration of ANG-2, FGF-2, HGF, IL-8, PDGF-BB, TIMP-1, TIMP-2, TNF-α, and VEGF that are the major cytokines involved in angiogenesis in MM and other cancers and, as previously demonstrated in MM patients, directly correlate with disease activity and increase with progression." (PMID 30626425, 2019). "Further interrogation of the TIMP2 co-expressed genes identified highly correlated core matrisome partners that are of interest as modulators for TIMP2 function, specifically in the TME, and are potentially useful either as targets or biomarkers of TME-directed cancer therapies." (PMID 31882975, 2019). "In the TIMP2 and TIMP4 co-expression profiles we observed distinct clustering for the carcinomas." (PMID 31882975, 2019). "TIMP-1, TIMP-2, MMP-2 and MMP-9 are cancer metastasis related expressions, Res and PA combination could raise TIMP-1, TIMP-2 and reduce MMP-2 and MMP-9 expressions in HepG2 cancer cells, and these effects were stronger than only PA treatment." (PMID 28978315, 2017). "Studies that show an increase in cancer cell migration as a result of MT1-MMP overexpression demonstrate migration enhancement ranging from 50 -500 %, whereas others show a requirement of TIMP-2 for MT1-MMP mediated migration enhancement." (PMID 27756325, 2016). "As tumors progress, TIMP-2 expression levels are decreased or absent in several types of human cancer, particularly in invasive and metastatic tumors." (PMID 24527080, 2014). "In cancer cells, MMP-2 and MMP-9 are controlled by their endogenous inhibitors TIMP-1 and TIMP-2." (PMID 23878609, 2013). "However, additional further studies are needed to establish the mechanisms for the inhibitory effects on cancer invasion by up-regulation of TIMP-1 and TIMP-2." (PMID 24018886, 2013). "As anticipated, a significant negative correlation was found between MMP and TIMP-2 secretion by all the female cancer cell lines tested." (PMID 22736175, 2012). "Therefore, the transcriptional repression of TIMP2 and TIMP3 by EZH2 likely enhances ECM degradation and angiogenesis but reduces apoptotic activity, favoring cancer cell invasion and metastasis." (PMID 22272343, 2012). "Clinical studies suggest that TIMP-2, or the ratio of MMP-2 and TIMP-2 expression, may play a critical role on cancer progression." (PMID 16776850, 2006). "Its major function in cancer progression is to directly degrade the extracellular matrix components, which are mainly type I–III collagen or indirectly type IV collagen through the activation of MMP-2 with a cooperative function of the tissue inhibitor of metalloproteinase-2 (TIMP-2)." (PMID 37681919, 2023). "Moreover, TIMP-1 and TIMP-2, known to inhibit angiogenesis, were also present in the ADSC-EVs, which is in agreement with previous studies showing that both TIMPs were secreted via EVs (bone marrow stem cells and cancer cells)." (PMID 33916460, 2021). "Specifically, CTD-2218G20.2 was predicted to interact with 86 proteins (Pearson correlation coefficient, PCC > 0.3), some of which, including PSG4, PSG5, and PSG7, could also interact with cancer-related proteins, including KISS1, TIMP2, MMP11, IGFBP1, EGFR, and CDKN1C." (PMID 32117443, 2020).
cancer (continued). "Furthermore, pectolinarigenin markedly impaired cancer cell migration and invasion by down-regulating phosphorylated-Stat3, and expression of matrix metalloproteinase (MMP)-2, MMP-9, while up-regulating the expression of TIMP2." (PMID 31649548, 2019). "Second, the ratios of MMPs/TIMP2 were considered meaningful markers for cancer studies but could not be evaluated currently." (PMID 29941993, 2018). "Third, our current study did not evaluate the prognostic role of TIMP2 on the following respects, such as its genetic variations like SNP and methylation, the expression locations including cancer and mesenchymal cells, and the detection samples like tissues and serum." (PMID 29941993, 2018). "In summary, we consider that the TIMP2-based and enediyne-integrated fusion protein LDP(AE)-TIMP2 could be a promising agent in cancer targeted therapy; without doubt, further validations of the drug are also needed." (PMID 26314845, 2015). "Although TIMP-2 has been shown to have A549 cell growth-stimulatory activity in previous reports, the effect of TIMP-2 on cell proliferation has remained controversial because other studies have shown that TIMP-2 inhibits cell proliferation in experiments that used the same types of cancer cells." (PMID 26556867, 2015). "TIMP2 hampers the growth of endothelial cells induced by basic fibroblast growth factor, thus suppressing angiogenesis and regulating apoptosis, indicates a negative role in cancer." (PMID 25136829, 2014). "In clinical studies for cancer treatments, use of MMP inhibitors has been associated with musculoskeletal side effects, so the ability of Ala-TIMP2 to provide beneficial effects without acting on MMPs may make it a more viable approach." (PMID 37321845, 2023). "Therefore, changes in TIMP-2 and MMP-2 levels (or MMP/TIMP-2 ratio) and activities would also determine whether TIMP-2 role is tumor promoting or inhibitory in a particular type of cancer." (PMID 26056585, 2014). "We have previously shown that knock down of TIMP-2 in T2-KD ovarian non-malignant (FT282) and cancer cells (OVCAR4 and JOSH2) had enhanced sensitivity to PTX compared to their matched controls." (PMID 36585738, 2022). "TIMP2, but not TIMP1, secreted by monocyte-like cells, is a potent suppressor of invadopodium formation in breast and pancreatic cancers." (PMID 34638439, 2021). "The inhibitory effect of TIMP-2-specific inhibition on MMP-2 (previous findings show a strong balance between MMP-2 and TIMP-2 in the case of cancer cells) can explain the observed lack of TIMP-2 overexpression in PsA patient plasma." (PMID 34691360, 2021). "In the present study, we further detected the protein level of TIMPs in human LoVo cancer cells that had been exposed to PGE2, which demonstrated that PGE2 treatment shows no influence on regulating TIMP-1, TIMP-2, TIMP-3 and TIMP-4." (PMID 21859479, 2011). "With respect to the cancer-specific mortality, the univariate analysis showed no significance for pT1a versus pT2a and TIMP-1 and TIMP-2 as a determinant factor, while the remaining 8 factors were significant factors of postoperative specific mortality of 247 patients." (PMID 27019657, 2016). "While both TIMP-1 and TIMP-2 were expressed in non-neoplastic lungs (NNL) as well as in carcinomas, stromelysin 3 (ST3), 92 kDa gelatinase and interstitial collagenase were expressed only by carcinomas." (PMID 1457364, 1992). "As the FGF2 rs1048201, PDGFRB rs246395, PDGFRA rs2228230, MMP2 rs243865, rs7201, and TIMP2 rs7501477 have not been previously examined in HNSCC in terms of survival and treatment outcome, this is most likely the first report describing their prognostic and predictive value in this type of cancer." (PMID 35406617, 2022).
infection (26 papers, 2008 to 2025). The state of being infected such as from the introduction of a foreign agent such as serum, vaccine, antigenic substance or organism. "As TIMP-2 plays a role in the regulation of MMPs, we hypothesize that TIMP-2 loss may contribute to the tissue destruction that occurs during severe infection." (PMID 30018884, 2018). "Additionally, sagA complemented GAS induces a 2-fold or greater loss in MCP-1, MCSF, MDC, MIP-1b, Thrombopoietin, and TIMP-2 compared to the SLS-deficient mutant infection." (PMID 30018884, 2018). "Here, we assayed MMP2, MMP7, MMP9, TIMP1, and TIMP2, which have previously been described to be differentially expressed after infection of the CNS." (PMID 30442185, 2018). "Additionally, the only two cytokines found to be reduced by 2-fold or more in both wild-type and sagA complemented infection compared to mock and SLS-deficient infection, respectively, were MDC and TIMP-2." (PMID 30018884, 2018). "It is of interest to address whether infection by other types of HPV in cervical tissues contributes to the difference of TIMP-2 expression." (PMID 23967226, 2013). "Additionally, TIMP-2 secretion was significantly decreased in the presence of C. albicans suggesting that there is a compromise in the basement membrane tissue integrity following infection." (PMID 39944725, 2025). "Wnt signaling molecules, genes associated with inflammation and infection, such as EBF1, TIMP2, COL4A3, TNF, and the candidate gene for schizophrenia, i.e., ABCA13, have been identified as PTB biomarkers through the multiple target studies, though their mechanisms remain unclear." (PMID 38391647, 2024). "Across studies, signals also favored collagen‐based care for earlier area reduction and, in one trial, fewer infection‐related withdrawals; mechanistic work showed reductions in MMP‐9/TIMP‐2." (PMID 41249888, 2025). "Knockdown of miR-20a, through infection of anti-miR-20a-LV, in SiHa cells increased ATG7 and TIMP2 protein levels." (PMID 25803820, 2015). "In this study, the expression of both MMP2 and TIMP2 increased during LX-2 activation induced by TGF-β1; however, after AdNDRG2 infection, MMP2 was enhanced while TIMP2 levels decreased compared with AdLacZ controls (MMP9 and TIMP1 were undetectable)." (PMID 22110735, 2011). "We observed an increase in the MMP-14 staining in the maternal stroma and caruncular epithelium of Nc-Spain1H placentomes at 10 dpi, whereas MMP-2 and TIMP-2 staining was not apparently modified by the infection (not shown)." (PMID 32552750, 2020). "To prove that TIMP-2 could inhibit HCT-116 cells invasion and migration by regulating MMP-9, we had a secondary lentivirus-infection to vary MMP-9 expression." (PMID 31293204, 2019). "Eighteen cytokines were elevated >2-fold relative to controls at 12 weeks of infection, including CD 30L, Fas ligand, Fractalkine, GCSF, IFN-γ, IL1-β, IL4, IL10, IL12p40/p70, IL12p70, IL17, I-TAC, Lymphotactin, MCP-1, MCSF, MIG, MIP-1α, and TIMP-2." (PMID 26079509, 2015). "In addition, we also demonstrate that an infection of VSMC with CAPN1 increases the transcription and protein expression of MT1-MMP, an activator of MMP2, and decreases protein levels of TIMP2, an inhibitor of MMP2 (Jiang LQ, unpublished data)." (PMID 18493299, 2008). "Live T. gondii tachyzoites, but not multiplicity of infection (MOI)-equivalent amounts of tachyzoite lysate, selectively induced elevated Timp1, but not Timp2, expression." (PMID 40265926, 2025). "Higher collagen deposition after infection in Cyb5r3 SPC–KO mice was accompanied by significantly higher transcript levels of Mmp12, Mmp13, Mmp14, and tissue inhibitor of metalloproteinases 1 (Timp1) but neither Timp2 nor Timp3." (PMID 36749633, 2023). "TIMP-2, -3 and to a lesser extent TIMP-4 mRNA were constitutively expressed at high levels within the CNS of naïve WT mice, but were not further up-regulated by infection." (PMID 24156369, 2013).
infection (continued). "Thus, filarial lymphedema with or without active infection is characterized by elevated levels of circulating TIMP-1 and TIMP-2 and decreased levels of TIMP-3." (PMID 22679524, 2012).